IL17A (interleukin 17A)
Diseases named in the same sentence as IL17A in open-access papers (continued):
Sharing a sentence is not in itself a finding about the gene and the disease.
epistaxis (1 paper, 2022). Bleeding from the nose. "As evidenced by the results of the present study, IL-17A is the main cytokine that participates in the pathogenesis of idiopathic epistaxis; moreover, in association with IL-10, it can be regarded as the suppressor of IFN- in patients with epistaxis." (PMID 35145935, 2022). "As evidenced by the results of the present study, IL-17A is the main cytokine which participates in the pathogenesis of idiopathic epistaxis; moreover, in association with IL-10, it can be regarded as the suppressor of IFN- in patients." (PMID 35145935, 2022). "The serum levels of IL-4, IL-10, IL-17A, IL-23, and IFN- were evaluated in 90 patients with idiopathic epistaxis and 90 healthy controls using enzyme-linked immunosorbent assay (ELISA) technique." (PMID 35145935, 2022). "The down-regulation of IFN- bolds the roles played by IL-17A in the pathogenesis of idiopathic epistaxis." (PMID 35145935, 2022). "The results pointed out that IL-17A and IL-10 serum levels were increased in patients with idiopathic epistaxis, as compared to those in the controls." (PMID 35145935, 2022). "The results demonstrated that IL-17A serum levels significantly increased (P<0.001) in patients with epistaxis (423.47±16.40 pg/mL), as compared to those in healthy controls (185.88±15.07 pg/mL)." (PMID 35145935, 2022). "Data analysis in the male and female patients with epistaxis, in comparison with male and female controls, also confirmed the results and revealed that the serum levels of IL-17A and IL-10, as well as IFN-, had the same patterns in all patients." (PMID 35145935, 2022). "Moreover, IL-23 is the main cytokine for the maintenance of the cells; therefore, this research project was designed to explore IL-17A and IL-23 serum levels in patients with epistaxis, in comparison with healthy controls." (PMID 35145935, 2022). "Due to the increased production of IL-10 in patients with epistaxis, it may be concluded that the up-regulation of IL-10 is a normal immune response to increased expression of IL-17A, performing regulatory functions to modulate tissue damage roles of IL-17A." (PMID 35145935, 2022). "The statistical analysis showed that IL-17A and IL-10 serum levels significantly increased and IFN- decreased in both male and female patients with epistaxis, as compared to those in male and female healthy controls, respectively (P<0.001 for all)." (PMID 35145935, 2022). "In the present study, IL-17A, IL-23, IFN-γ, IL-4, and IL-10 serum levels were compared between patients with idiopathic epistaxis and normal controls." (PMID 35145935, 2022). "Nonetheless, IL-17A (P=0.325), IL-23 (P=0.930), IFN- (P=0.860), IL-4 (P=0.313), and IL-10 (P=0.158) serum levels did not change in epistaxis patients with and without a familial history of epistaxis." (PMID 35145935, 2022). "Furthermore, IL-17A (P= 0.760), IL-23 (P=0.658), IFN- (P=0.961), IL-4 (P=0.370), and IL-10 (P=0.487) serum levels did not change in female and male patients with epistaxis." (PMID 35145935, 2022).
Exotropia (1 paper, 2021). A form of strabismus with one or both eyes deviated outward. "The levels of IL-6, IL-10, IL-17A, IL-12P70, INF-γ, and TNF-α were detected in tears in patients with concomitant exotropia and healthy controls matched by age and gender through the Simoa technology." (PMID 34659636, 2021).
female infertility (1 paper, 2019). Diminished or absent ability of a female to achieve conception. "Elucidation of therapeutic strategies for the selective pre-pregnancy inhibition of IL17A in promoting peri-conceptional expansion of Tregs and/or attenuating Th17 subsets may have important implications for therapy of PCOS-associated female infertility." (PMID 31024070, 2019).
fibroids (1 paper, 2024). "Patients with fibroids had uniquely decreased levels of IL-17A (q = 0.023), EGF (q = 0.034), and an elevation of macrophage inflammatory protein-1 beta (MIP-1β) (q = 0.040)." (PMID 38972981, 2024).
folate deficiency (1 paper, 2023). A nutritional condition produced by a deficiency of FOLIC ACID in the diet. "Our study demonstrated that T-cell cytokines, such as IL-2, IFN-γ, and IL-17A/F were significantly increased by the HFF diet, but not folate deficiency." (PMID 37630806, 2023).
gangrene (1 paper, 2025). Death of tissue, usually in considerable mass and generally associated with loss of vascular (nutritive) supply and followed by bacterial invasion and putrefaction. "Through a systematic analysis of 12 drugs and six key genes (IGF1, IL17A, ACE, FGF2, IL6 and TLR4), we have provided a new scientific perspective on gangrene prevention in diabetic patients." (PMID 40657379, 2025).
gastroesophageal disease (1 paper, 2024). A class of gastroenterological diseases involving the stomch and or esophagus. "Although the pathophysiology of iSGS is unclear, estrogen, IL-17A/IL-23 axis, and gastroesophageal disease may play a role." (PMID 39872570, 2024).
Hepatomegaly (1 paper, 2021). Abnormally increased size of the liver. "Taken together, hepatomegaly might be associated with IL-17A in our DENV-4 patients." (PMID 34447698, 2021).
Hernia (1 paper, 2023). "Overall, these results seem to indicate a possible mechanism for macrophage-induced hernia regression via macrophage activation and phagocytic capacity through IL4, IL17a, IL18, and RANTES and intensified tissue remodeling mediated by LIX." (PMID 37429889, 2023). "Furthermore, a possible mechanism for macrophage-induced hernia regression and tissue repair was unveiled through IL4, IL17a, IL18, LIX, and RANTES increase." (PMID 37429889, 2023).
Hypercalcemia (1 paper, 2020). An abnormally increased calcium concentration in the blood. "In the present series of PHPT patients, mean levels of circulating IL-17A, likely derived from bone resident lymphocytes and osteoblasts, were higher in PHPT women with mild hypercalcemia and calciuria with respect to PHPT women with more severe hypercalcemia and hypercalciuria." (PMID 32256191, 2020).
Hyperhidrosis (1 paper, 2025). Abnormal excessive perspiration (sweating) despite the lack of appropriate stimuli like hot and humid weather. "IL-17A expression in sweat gland tissues was upregulated in hyperhidrosis mice but significantly decreased after SR2211 treatment (p < 0.01), while GAPDH served as a loading control." (PMID 41181099, 2025).
Hypertonia (1 paper, 2020). A condition in which there is increased muscle tone so that arms or legs, for example, are stiff and difficult to move. "Regarding tone disorders, we found significantly higher levels of proinflammatory mediators (GM-CSF, IL-6, and IL-17A), and the anti-inflammatory IL10, in children with hypertonia than in those with hypotonia." (PMID 33584663, 2020).
Hypocalcemia (1 paper, 2025). An abnormally decreased calcium concentration in the blood. "Chronic hypocalcemia promotes an inflammatory microenvironment by activating the TRPV6 calcium channel, which enhances the differentiation of Th17 cells and the secretion of IL-17A." (PMID 40766324, 2025).
infectious mononucleosis (1 paper, 2021). A condition characterized by an increase in mononuclear white blood cells and swollen lymph nodes, which is usually caused by infection with the Epstein-Barr virus. "In support of this hypothesis, EBV-positive infectious mononucleosis patients display a significant increase in IL-17A-producing CD4+ T cells, an increase that persists at least 1 month following the resolution of clinical symptoms." (PMID 33824206, 2021). "The fact that EBV-positive infectious mononucleosis patients have a significant increase in IL-17A-producing CD4+ T cells for at least a month following symptoms supports the idea that gammaherpesviruses that lack an IL-17A homologue usurp host IL-17A signaling to promote infection." (PMID 33824206, 2021).
ischemic disease (1 paper, 2021). Lack of blood supply to an area of the body, resulting in impairment of tissue oxygenation. "IL-17A and ER stress play important roles in promoting angiogenesis of ischemic diseases." (PMID 33933165, 2021).
lichen planopilaris (1 paper, 2024). Lichen planopilaris (LPP) is an inflammatory condition that causes patchy hair loss, mainly on the scalp. "The number of IL-17A-producing cells was also the highest in oral LP compared to all other LP subtypes (classical LP 2.39%, genital LP 1.54%, lichen planopilaris 1.18%)." (PMID 39273670, 2024). "Further, the dermis of lichen planopilaris showed a lower presence of IL-17A-producing cells (1.18%) compared to oral LP (8.02%) but not compared to the other examined LP subtypes." (PMID 39273670, 2024).
lung mucoepidermoid carcinoma (1 paper, 2022). "Moreover, IL-17A is known to stimulate upregulation of SLC26A4, an anion exchange protein which is known to induce goblet cell hyperplasia in human lung mucoepidermoid carcinoma cells and murine airway epithelial cells." (PMID 35773318, 2022).
Lymphatic Metastasis (1 paper, 2020). Transfer of a neoplasm from its primary site to lymph nodes or to distant parts of the body by way of the lymphatic system. "In the study, we clarified that the serum levels of IL-17A were associated with lymphatic metastasis and advanced stages." (PMID 32489459, 2020).
lymphoepithelioma (1 paper, 2023). "In our collected cases, IL-17A was observed to be expressed in lung squamous carcinoma, adenocarcinoma, and lymphoepithelioma-like carcinoma, and mainly expressed in the cytoplasm and nucleus of tumor cells." (PMID 37978543, 2023).
macular holes (1 paper, 2024). A hole in the macula of the retina. "IL-17A levels in the vitreous humor of 31 PDR patients and 32 eyes with macular holes in the anterior retina were measured by ELISA after vitrectomy." (PMID 38711982, 2024).
metastasis (1 paper, 2024). The spread or migration of cancer cells from one part of the body (where they first appeared) to another. "In the context of tumor promotion, several studies have reported an increased abundance of Th17 cells in the OC TME,30, 72, 73 and the abundance of tumor‐infiltrating IL‐17A‐producing producing γδ T cells correlated with larger tumor size and lymph node metastasis." (PMID 38566518, 2024).
metastatic colorectal cancer (1 paper, 2017). "Among individual Th17-related potential biomarkers, only baseline serum IL-17A concentrations are herein associated with PFS in patients with metastatic colorectal cancer treated with a bevacizumab-based chemotherapy." (PMID 28347290, 2017). "In this ancillary study, baseline serum IL-17A concentration is the only Th17/IL-17 related factor that was significantly associated with the response of patients with metastatic colorectal cancer to bevacizumab." (PMID 28347290, 2017). "In a near future, it would be interesting to target IL-17A, concomitantly or sequentially to VEGF inhibition, to overcome resistance to anti-VEGF-based therapy in metastatic colorectal cancer." (PMID 28347290, 2017). "In our study we observed no influence of IL-17A and IL-17F polymorphisms on OS and PFS of our bevacizumab-treated group of patients with metastatic colorectal cancer." (PMID 28347290, 2017).
myeloproliferative neoplasm (1 paper, 2025). A clonal hematopoietic stem cell disorder, characterized by proliferation in the bone marrow of one or more of the myeloid (i.e., granulocytic, erythroid, megakaryocytic, and mast cell) lineages. "It will be of interest to determine whether, in addition to a physiological role in the erythroid stress response, IL-17A contributes to myeloproliferative neoplasms such as polycythemia vera, where it might synergize with the constitutively active JAK2V617F in erythrocyte over-production." (PMID 41379768, 2025).
nephrosclerosis (1 paper, 2017). Hardening of the kidney due to infiltration by fibrous connective tissue (fibrosis), usually caused by renovascular diseases or chronic hypertension. "Statistically significant correlations were established between IL-17A, TGF-β, and D (excretion rate of 99mTc-technephore from the parenchyma) and Rnfsc (a stable sign of nephrosclerosis), respectively." (PMID 29201463, 2017).
non-Hodgkin lymphoma (1 paper, 2021). Distinct from Hodgkin lymphoma both morphologically and biologically, non-Hodgkin lymphoma (NHL) is characterized by the absence of Reed-Sternberg cells, can occur at any age, and usually presents as a localized or generalized lymphadenopathy associated with fever and weight loss. "Further, IL-17A stimulation of primary B cells from non-Hodgkin lymphomas promoted proliferation in vitro, while stimulation also enhanced tumor proliferation and angiogenesis in vivo." (PMID 33824206, 2021).
normal pressure hydrocephalus (1 paper, 2024). A form of compensated hydrocephalus characterized clinically by a slowly progressive gait disorder (see gait disorders, neurologic), progressive intellectual decline, and urinary incontinence. "Next, we selected GMs causally associated with normal-pressure hydrocephalus and obstructive hydrocephalus, given that IL-17A and IL-27 are known to be associated with these conditions." (PMID 39076985, 2024). "Rigorous MR analysis revealed that IL-17A reduces the risk of obstructive hydrocephalus, while IL-27 reduces the risk of normal-pressure hydrocephalus." (PMID 39076985, 2024). "We first confirmed that Firmicutes (phylum) reduces the risk of obstructive hydrocephalus by increasing the levels of IL-17A." (PMID 39076985, 2024). "After removing confounders, univariable and multivariable MR analyses were performed using summary statistics to assess the causal relationships between GM, inflammatory factors (IL-17A and IL-27), and types of hydrocephalus." (PMID 39076985, 2024). "Furthermore, we found that IL-17A and IL-27 reduced the risk of obstructive hydrocephalus and normal-pressure hydrocephalus, respectively." (PMID 39076985, 2024). "In addition, Firmicutes (phylum) decreased the risk of obstructive hydrocephalus by increasing levels of IL-17A (mediating effect = 21.01%), while Eubacterium ruminantium group (genus) increased the risk of normal-pressure hydrocephalus by decreasing levels of IL-27 (mediating effect = 7.48%)." (PMID 39076985, 2024). "Specifically, the Firmicutes (phylum) could reduce the risk of obstructive hydrocephalus by increasing the levels of IL-17A, while the Eubacterium ruminantium group (genus) potentially increased the risk of normal-pressure hydrocephalus by decreasing the levels of IL-27." (PMID 39076985, 2024). "Furthermore, Firmicutes (phylum) reduced the risk of obstructive hydrocephalus by increasing the concentrations of IL-17A, whereas the Eubacterium ruminantium group (genus) potentially increased the risk of normal-pressure hydrocephalus by decreasing the concentrations of IL-27." (PMID 39076985, 2024). "Thus, Firmicutes (phylum) is inextricably linked to inflammation and may reduce the risk of obstructive hydrocephalus by enhancing the gut barrier and lymph angiogenesis via IL-17A." (PMID 39076985, 2024). "We reveal the connection between GM, inflammatory factors (IL-17A and IL-27), and hydrocephalus, which lays the foundation for unraveling the mechanism between GM and hydrocephalus." (PMID 39076985, 2024). "To explore the pathophysiological mechanisms of inflammatory factors in hydrocephalus, we analyzed IL-17A and IL-27, key players in inflammatory activation and immunoprotection." (PMID 39076985, 2024). "Therefore, enhancing infection barrier function and promoting lymphatic drainage may explain the protective effect of IL-17A on obstructive hydrocephalus." (PMID 39076985, 2024).
obsessive-compulsive disorder (1 paper, 2023). A disorder characterized by the presence of persistent and recurrent irrational thoughts (obsessions), resulting in marked anxiety and repetitive excessive behaviors (compulsions) as a way to try to decrease that anxiety. "In children and adolescents with obsessive-compulsive disorder, an increase in Th17 lymphocytes and IL-17A was found, but their level did not always correlate with the duration and severity of obsessive-compulsive disorder symptoms." (PMID 38067176, 2023).
obstetric disorder (1 paper, 2025). Disorder associated with pregnancy, childbirth, and puerperium. "Th17 cells contribute to successful pregnancy outcomes through the secretion of IL-17A and IL-17F, having also been implicated in the pathophysiology of obstetric disorders." (PMID 40894398, 2025).
oligohydramnios (1 paper, 2023). A lower than normal quantity of amniotic fluid in the amniotic sac as compared to normal values. "Our study showed that the use of CS was related in combination with premature delivery of SGA and oligohydramnios to high levels of IL-17A in the 3rd trimester, in pregnant women with AS and PsA." (PMID 36650451, 2023).
oral cavity cancer (1 paper, 2020). A primary or metastatic malignant neoplasm involving the oral cavity. "It is necessary to conduct further tests to confirm the usefulness of estimation of IL-17A in saliva in the diagnosis, clinical prognosis, and monitoring of the effects of treatment of oral cavity cancer." (PMID 32855976, 2020).
oropharyngeal cancers (1 paper, 2020). Carcinoma, predominantly squamous cell, arising from the epithelial cells of the oropharynx. "The concentrations of IL-17A, IL-17F, IL-17E/IL-25, and TNF-α in saliva samples in the patients diagnosed with oral and oropharyngeal cancer was correlated with the disease stage as well as with T, N, and M parameters separately." (PMID 32855976, 2020). "The aim of this study was to assess levels of IL-17A, IL-17E/IL-25, IL-17F, and TNF-α in the saliva in patients with oral and oropharyngeal cancer, depending on the degree of malignancy and bacteriological cultures from the oral cavity as potential biomarkers of cancer." (PMID 32855976, 2020).
Pasteurella multocida infection (1 paper, 2023). "It was also found that P0910 and ΔOmpH in Pasteurella multocida infection activated the expression of ropE, HSPBP1, FERH, ATP10A, ABCA13, RRP7A, IL-10, IFN-γ, IL-17A, EGFR and dnaJ." (PMID 36977260, 2023).
pasteurellosis (1 paper, 2025). Infections with bacteria of the genus pasteurella. "Our findings suggested that targeting the Th17 cell/IL-17A activation pathway may be a potential strategy for the treatment of pasteurellosis and other respiratory bacterial diseases." (PMID 41402924, 2025). "Therefore, on the basis of our previous study, we further systematically explored the role of Th17 cells/IL-17A in pasteurellosis." (PMID 41402924, 2025). "Importantly, our findings suggested that targeting the Th17 cell/IL-17A activation pathway may be a potential strategy for the treatment of pasteurellosis and other respiratory bacterial diseases." (PMID 41402924, 2025). "Therefore, targeting Th17 cells/IL-17A could be a potential strategy for the treatment of pasteurellosis and other respiratory bacterial diseases." (PMID 41402924, 2025).
peripheral arterial disease (1 paper, 2022). A disorder of the arteries supplying the upper and lower extremity and the visceral organs. "In skeletal muscle, the expression of TNF-alpha, INF-gamma, IL-17A, IL-6, CCL5, and TGF-beta were increased in patients with peripheral arterial disease (PAD)." (PMID 36579591, 2022).
Rectal prolapse (1 paper, 2014). Protrusion of the rectal mucous membrane through the anus. "IFN-γ−/−IL-2Rα−/− and IL-2Rα−/−, but not IL-17A−/−IL-2Rα−/− mice frequently suffered from rectal prolapse and diarrhea." (PMID 25133396, 2014).
subacute thyroiditis (1 paper, 2023). Self-limited inflammation of the thyroid gland characterized by the presence of multinucleated giant cells. "He relapsed twice after reinitiation of the drug Another case (published in 2021) introduced a 71-year-old male patient with PsA who was treated with secukinumab (IL-17A inhibitor), which was later switched to adalimumab (TNF-α inhibitor), while developing subacute thyroiditis." (PMID 36902323, 2023).